CD44 (CD44 molecule (IN blood group))
Diseases named in the same sentence as CD44 in open-access papers (continued):
Sharing a sentence is not in itself a finding about the gene and the disease.
tumor (continued). "Androgen deprivation therapy promotes the expansion of cancer stem cells (CSCs) by altering the tumor microenvironment and upregulating key stem cell markers, including OCT4, SOX2, NANOG, CD133, and CD44, driving tumor initiation, progression, and recurrence in PCa." (PMID 40722714, 2025). "Inhibiting the interaction between CD44 and hyaluronic acid reduces tumor cell motility." (PMID 40635786, 2025). "Since the literature suggests that pituitary ACTH-secreting tumors may contain both EpCAM-positive tumor cells and CD44-positive tumor stromal fibroblast-like cells, we quantified the populations of EpCAM+ and CD44+ cells via flow cytometry analysis." (PMID 40002253, 2025). "Similarly, in some tumors, tumor cells with high OPN expression can inhibit T cell function through CD44." (PMID 40093009, 2025). "bound a layer of hyaluronic acid to the surface of the photosensitizer zinc phthalocyanine (ZnPc-Si), and selective interactions between the hyaluronic acid and CD44 on the surface of the tumor cells increased ZnPc-Si cellular internalization and enhanced its PDT efficacy." (PMID 40809017, 2025). "For the Epi_C1 clusters, we further classified cells into CD44-positive and CD44-negative clusters based on CD44 expression, referring to them as CD44+ and CD44- Epi_C1, respectively, to explore the specific functions of CD44+ tumor cells at the leading edge of CRC tissues." (PMID 40069574, 2025). "Overall, while STAT3 inhibition did not significantly impact cell viability, proliferation, or CD44 induction after HER2 inhibition, JAK1 inhibition appeared to sensitize cells to HER2 inhibition and impair proliferation during the recovery phase in CD24+/CD44+ tumor cells." (PMID 40430044, 2025). "To further understand whether LMO2 regulates the intermediate epithelial-mesenchymal state, we utilized CD104 and CD44, which have been previously demonstrated to mark hybrid E/M cells in breast cancer." (PMID 40709263, 2025). "As a result, HA has been widely studied in targeting CD44 and tumor migration." (PMID 41259528, 2025). "Similarly, targeting modifications based on tumor microenvironment markers (such as CD44) can enhance tumor cell uptake of siRNA, thereby improving efficacy." (PMID 41304744, 2025). "This spatially resolved sender–receiver pairing provides mechanistic support for functional ligand transmission from apoptosis-high cancer cells to CD44-expressing immune populations, reinforcing the critical role of the SPP1–CD44 axis in mediating tumor–immune interactions." (PMID 41201629, 2025). "Notably, CD44 expression consistently predicts lymph node metastasis, highlighting CD44’s role as a marker of tumor invasion and aggressiveness." (PMID 41465166, 2025). "In breast cancer, LMW-HA activates tumor-promoting signaling through CD44 and Yes-associated protein (YAP), but HMW-HA does not." (PMID 39946200, 2025). "Additionally, CD44 is involved in regulating the tumor microenvironment and interacts with various signaling pathways, such as Wnt, TGF-β, and EGF pathways." (PMID 40046628, 2025). "Moreover, according to some data, the expression of CD44 isoforms can be plastic, depending on the tumor stage." (PMID 39851489, 2025). "2demonstrated that combining PIT targeting CD44 with interleukin‐15 (IL‐15), a cytokine that activates natural killer cells, enhances antitumor immunity, leading to stronger tumor growth suppression, prolonged survival, and increased CD8+ T‐cell infiltration compared to monotherapies." (PMID 40970572, 2025). "Heterogeneous vascular endothelial cellscan secrete molecules such as MIF and APP, which act on macrophagesurface molecules or complexes such as CD74 and CD44, inhibiting macrophagepolarization toward the antitumor M1 phenotype and promoting polarizationtoward the pro-tumor M2 phenotype." (PMID 40834268, 2025).
tumor (continued). "Finally, sender–receiver mapping demonstrated that SPP1 expression (Sender) was predominantly localized in tumor epithelial regions, while CD44 (Receiver) was enriched in immune cell–dense zones, particularly around macrophages and monocytes." (PMID 41201629, 2025). "Incoming signals to PIAS1+ TAMs from tumor cells included elevated MIF–CD74_CD44 and MIF–CD74_CXCR4 interactions, which in this context may promote M1 polarization." (PMID 40941002, 2025). "CD44 is crucial for T cell navigation within the tumor stroma." (PMID 40995371, 2025). "Remarkably, the CD44-IR700_IT group exhibited a smaller tumour volume than the CD44-IR700_IV group." (PMID 39848206, 2025). "We revealed distinct spatial patterns: Lgr5-positive niches were predominantly localized in the central areas of the tumor, Alcam- and Prom1-positive niches were dispersed throughout the tumor regions, while CD44-positive niches were predominantly distributed in the outer regions." (PMID 40069574, 2025). "CD44 is a non-kinase transmembrane glycoprotein, and its high expression is associated with enhanced migration and invasion of tumor cells and resistance to chemotherapy." (PMID 40942197, 2025). "Additionally, CD44 and TNFSF14 were found to be positively associated with Tregs, which are known to suppress the immune response and promote tumor growth." (PMID 39977830, 2025). "In addition, hyaluronic acid (HA) was utilized to create the nano-delivery tool, resulting in the HER2/CD44-targeted hydrogel nanobot, ALPR, effectively delivered to HER2/CD44 expressing tumor cells." (PMID 40465130, 2025). "Together, these mechanisms position CD44 as a dynamic regulator of tumor cell behavior." (PMID 41440277, 2025). "Inhibiting CD44 expression significantly reduces tumor clonogenicity and tumorigenic potential." (PMID 40635786, 2025). "Hypoxia increased VEGF release from tumor spheres, particularly upon CD44 kd." (PMID 37849446, 2024). "As recent studies have shown the clinical effectiveness of topical HA formulations in the reduction or prevention of mucositis in cancer patients undergoing chemotherapy, it is important to better understand the systemic and tumour-specific effect of the CD44–HA axis in clinical settings." (PMID 38542115, 2024). "By contrast, when we overexpressed P65 in LS174T sh-RK cells, we discovered that downregulation of CD44 could be rescued, along with the ability to form tumor spheres and migrate." (PMID 38902257, 2024). "Overexpression of CD44 can be observed in the cell membrane of some malignant tumor cells." (PMID 38318188, 2024). "Key differences involved enhanced communication in BR1 from the tumor cell cluster enriched in immune and cell-cycle-MPs (T2) to reactive microglia states (Mg9, Mg12–13), including upregulation of the microglia-activating MIF_CD74_CD44 axis." (PMID 39372744, 2024). "Importantly, CD44 has emerged as a CSC marker in several tumor types (e.g., breast, colorectal, lung, and pancreatic cancer)." (PMID 39062846, 2024). "Moreover, hepatocytes used in the experiments can selectively uptake tumor exosomes with high expression of CD44." (PMID 38736891, 2024). "Furthermore, the presence of SPP1+ macrophages in the triad structure, alongside endothelial and POSTN+ FAP+ CAFs, suggests a role in promoting tumor development through pro‐angiogenic properties and activation of CD44 in tumor cells." (PMID 39716897, 2024). "However, the individual expression of CD133 and CD44 was found to be marginally associated with moderately differentiated histology of the tumor and PNET-type tumor, respectively." (PMID 39148690, 2024). "All mice had to be euthanized due to tumor ulceration except two animals of the CD44 kd group." (PMID 37849446, 2024). "Although CD44 is a well-known marker of CSCs and plays important roles in tumor initiation and development, the upstream and downstream regulatory mechanisms of CD44 remain unclear." (PMID 39145451, 2024).
tumor (continued). "Notably, our findings revealed a consistent upregulation of N-cad and CD44 expression across all three tumor tissue regions in conjunction with reduced β-cat membranous staining, and these differences were statistically significant." (PMID 38903413, 2024). "Pro-angiogenic factors promote CD44 expression on tumour vasculature ECs." (PMID 38791985, 2024). "Moreover, CD44 offers an additional role within the immune system, that has the potential to aid in immune escape and to promote tumour progression." (PMID 38816670, 2024). "In the RFP+ tumor sites, we analyzed the relative area covered by CD44 labelling." (PMID 38566120, 2024). "Additionally, inhibiting cell proliferation and tumor sphere formation cultured in 3D environment was found to depend on CD44 inactivation." (PMID 38783892, 2024). "In addition to mediating cellular adhesion to the cell-extracellular matrix, CD44 plays important roles in the differentiation, invasion, and metastasis of tumor cells 9-11." (PMID 38903932, 2024). "In addition, fibroblast cells also regulate T cells through laminin-CD44, making T cell activity and efficacy decrease with the tumor progression." (PMID 38278958, 2024). "Importantly, we investigated the downstream regulatory mechanism of POLE2, and found that POLE2 inhibited the ubiquitination degradation of CD44 to promote tumor progression." (PMID 38627379, 2024). "The relationship in neoplastic diseases between CD44 and its ligands is complex, and the expression of the two may be positively or negatively correlated." (PMID 38783892, 2024). "Accordingly, tumors of Bio-nFeR-treated mice showed a contraction of the CD44+/CD24− population, a reduced expression of stem cell-associated ALDH1, lower content of colony-forming units, and decreased frequency of tumor-initiating cells upon second transplantation in immunocompromised mice." (PMID 39497135, 2024). "Moreover, the restoration of Tgfb1 expression in MC38 tumor cells had a comparable impact to exogenous TGF-β1 in mitigating the tumor suppression and CD44+CD8+ T cell activation induced by Atp6v0a1 depletion." (PMID 38971819, 2024). "CD44+ colorectal cancer cells have both strong colony-forming and tumor-initiating capabilities." (PMID 39981299, 2024). "CD44, a cell surface molecule, is widely expressed in multiple cell types, including tumor cells." (PMID 38277205, 2024). "Subsequently, Günthert and colleagues discovered that an isoform of CD44 could modify the aggressiveness of a tumor by giving it metastatic properties when inserted into its genetic sequence." (PMID 38672650, 2024). "CD44 was present focally in control brains at similar intensity than in tumor tissue." (PMID 39473196, 2024). "Therefore, the role of CD44 in regulating the properties of CSCs and tumor cell signaling pathways makes it a critical factor in developing drug resistance." (PMID 38672650, 2024). "Finally, the relative abundance of CD44+CD62L− T effector cells in tumor-draining lymph nodes (tdLNs) was higher in DCP-IL-12/FLT3L-treated mice, suggesting activation of a systemic T cell response." (PMID 37996514, 2024). "Importantly, the levels of cytotoxic cytokines in CD44+CD8+ T cells were also significantly enhanced in the orthotopic (cecal) MC38 tumor model as a result of Atp6v0a1 knockdown." (PMID 38971819, 2024). "Nanocarriers prepared from HA-based amphiphilic block copolymers, including prodrug, dendrimers, or micelles, can not only reduce phagocytosis by the reticuloendothelial system (RES), but also achieve active targeting of tumor cells due to the overexpression of CD44." (PMID 38675130, 2024). "Furthermore, the protein level of CD74 expression was found to be expressed along with ALDH compared to the moderate expression level of CD24 and CD44 in the PDX tumor models." (PMID 39056676, 2024). "However, the CD11b+CD44+PD-L1+ cell population had high PD-L1 expression, which led to increased tumor immune escape." (PMID 38822322, 2024).
tumor (continued). "Furthermore, a new liposome‐based approach has been developed to install a targeting carbohydrate ligand, i.e., hyaluronan, onto the SERS‐NPs bestowing significantly enhanced binding affinity to its biological receptor CD44 overexpressed on tumor cell surface." (PMID 39185268, 2024). "Moreover, knockdown of Circ-0075305 notably facilitated the growth of GC tumor spheres and upregulated CD44 and NANOG expression." (PMID 38714724, 2024). "The best in vivo anti-tumor effect of HA-Lip-ICT can be attributed to both the passive targeting mediated by the EPR effect and the active targeting facilitated by the interaction between HA and CD44, as well as the accelerated release of ICT caused by the faint acidic tumor microenvironment." (PMID 39055490, 2024). "Furthermore, the iso-ligand receptors MIF-(CD74+CXCR4) and MIF-(CD74+CD44) regulate T/NK cells, potentially facilitating tumor cell evasion of immune surveillance." (PMID 39712016, 2024). "Moreover,ΔNp63α overexpression of 786-O and ACHN tumor spheres significantly increasedthe protein expression levels of RCSCs markers CD44, Oct4, and SOX2 comparedwith the control group." (PMID 38985013, 2024). "Additionally, they also demonstrated that recruiting monocytes increases the invasiveness of tumor cells via monocyte-activated CD44–VCAM-1 binding." (PMID 38590654, 2024). "In addition, clinical evidence suggests that highly expressing CD44 is a potential biomarker, including poor prognosis, tumor grade, and potential malignancy." (PMID 38783892, 2024). "Notably, the interaction between COL1A1 and CD44 emerged exclusively in the tumor group, underscoring a tumor-specific communication signature." (PMID 39165361, 2024). "This suggests that FABP6+ tumor cells may utilize CD74 to interact with CD44 on Treg cells, potentially promoting the immunosuppressive function of Treg cells and facilitating tumor development." (PMID 38277205, 2024). "Moreover, HMMR's interaction with low molecular weight hyaluronic acid (HA) fragments notably enhances immune cell recruitment and exacerbates patient prognosis by activating tumor microenvironment dynamics and influencing pathways such as CD44 expression." (PMID 38740918, 2024). "The role of ALDH1A1 and CD44 in OS as biologic markers of a subset of tumor cells that may confer treatment resistance has yet to be clinically evaluated or validated." (PMID 38371078, 2024). "The interaction between CD74 and CD44 may influence tumor cell behavior through the regulation of cell-matrix interactions, cell adhesion, migration, and infiltration pathways." (PMID 38277205, 2024). "CP1-LVs selectively adsorbed a large amount of tumor microenvironment-related protein and showed the enhanced internalization in tumor cells and tumor accumulation, which was attributed to synergism of various proteins, such as CD44, OPN, and other proteins overexpressed in tumors." (PMID 38326312, 2024). "Thus, we theorize upregulation of CD44 helps pathogens to infiltrate host cells and promote tumor formation by utilizing ERBB1 and ERBB2." (PMID 39981299, 2024). "There are limitations to the NP-ICG-HA multimodalimaging platform.Although CD44 is an exciting target and is overexpressed on breastcancer, as the tumor is highly heterogeneous, theremay be populations of cancer cells low in CD44 expression, which willescape the detection." (PMID 38757711, 2024). "In contrast, differentially expressed genes between CECs isolated using the cmHsp70.1 mAb- versus EpCAM mAb-based approach, such as ROCK2, STAT3 and CD82, are related to EMT, stemness and endometrial cell proliferation, which are regulated via up-regulated CD44/STAT3 signaling in tumor cells." (PMID 39519195, 2024). "This could help to understand the intricate interplay between RT, CD-44 expression, and cellular spreading behaviour, shedding light on the dynamic response of tumour cells to treatment." (PMID 38172135, 2024).
tumor (continued). "Consequently, HA modification prolongs drug circulation and enhances nanocarrier affinity to CD44-overexpressing tumor cells, increasing their growth-inhibitory effects." (PMID 38337294, 2024). "Moreover, CP1-LVs adsorb abundant tumor distinctive proteins, such as CD44 and osteopontin in tumor interstitial fluids, mediating selective tumor cell internalization." (PMID 38326312, 2024). "CD44 has been widely implicated as a cancer stem cell (CSC) marker, but it is widely expressed in the stromal and immune cells at a higher level than in the tumor cells." (PMID 39223689, 2024). "In addition, CD44 upregulation promoted tumor cells proliferation, tumor stem cell differentiation and drug resistance." (PMID 38627379, 2024). "Additionally, HA-modified magnetic NPs successfully illuminated tumors on MRI, suggesting their potential as a molecular imaging agent for CD44-targeted tumor detection." (PMID 39771471, 2024). "We also examined the correlation of CD44 expression with neovascularization in tumor stroma." (PMID 38796656, 2024). "Furthermore, a limited number of studies also investigated different expressions regarding CD44 molecules in the central part and in the periphery of the tumor." (PMID 39768912, 2024). "They highlighted that the progression associated with KRT5/6 could be significant for assessing its role as a prognostic marker and CD44 as a recurrence marker, although the cohort used was heterogeneous in terms of tumour stage and grade." (PMID 39594166, 2024). "Moreover, knockdown of CD44 inhibited the tumor-promoting effects of POLE2 overexpression on OS cells." (PMID 38627379, 2024). "Significantly, just a single CD44+ cell from a human tumor could be xenografted subcutaneously to produce a heterogeneous tumor containing the same cell types as found in the normal colon." (PMID 37832945, 2024). "CD44 overexpressed in many tumors is a cell-surface glycoprotein involved in cell adhesion and migration, and has been reported to be the major hyaluronan (HA)-receptor to target tumor sites." (PMID 38326312, 2024). "Tumor sphere assays evaluation revealed the remarkable reduction the sphere-forming ability of CD44( + )-OSCC cells following METTL3 knockdown, which could be partially reversed it by SALL4 overexpression." (PMID 38355684, 2024). "In addition, high levels of cholesterol can promote the entry of CD44 into lipid rafts, resulting in decreased binding between CD44 and Ezrin and subsequently inhibiting the migration and invasion of tumor cells." (PMID 38736891, 2024). "In addition, accumulating evidence suggests that miRs binding to CD44 plays key roles in drug resistance, tumor growth, and stemness." (PMID 38783892, 2024). "Moreover, it would enhance in vivo tumor targeting and demonstrate remarkable anti-tumor efficacy against liver cancer through CD44-mediated endocytosis." (PMID 39055490, 2024). "IHC staining of these xenograft tumours for previous stem cell-like markers, compared to the control xenograft tumours, showed that the percentage of CD44, NANOG, SOX9, SOX2 positive cells was reduced in the STC1-silenced group, and STC1 shRNA and circUBA2 co-transfection played a reversal role." (PMID 39103836, 2024). "The concordant changes in protein expression results with the values detected at the gene expression can be observed in all the evaluated parameters of integrin αV, brevican, CSPG-5, versican, integrin β-5, and CD44 and only in tumor staining in the case of MDM2, MMP2, and FLT-4." (PMID 39595920, 2024). "Other tumor sample analysis have also described this aggressive feature of CD44 staining." (PMID 39430073, 2024). "CD44 plays a crucial role in preserving the stemness and function of CSCs during tumor progression." (PMID 38672650, 2024).